BCL2 (BCL2 apoptosis regulator)
Diseases named in the same sentence as BCL2 in open-access papers (continued):
Sharing a sentence is not in itself a finding about the gene and the disease.
ovarian carcinoma (365 papers, 1998 to 2026). A malignant neoplasm originating from the surface ovarian epithelium. "Although mechanisms underlying the development of chemoresistance are still ambiguous, the B-cell lymphoma-2 (Bcl-2) family is closely associated with chemoresistance in ovarian cancer." (PMID 39021835, 2024). "We found a similar relationship in our study regarding BCL2 expression and polymorphic variants affecting BCL2 expression between patients with ovarian cancer and the control group." (PMID 38003498, 2023). "Urinary bcl-2 levels are elevated in patients with ovarian cancer and have diagnostic and prognostic significance." (PMID 38068422, 2023). "In ovarian cancer cells, curcumin decreased Bcl-2 expression while it increased Bax and caspase-3, causing cell cycle arrest in the G2/M stage and consequent cell death." (PMID 36903316, 2023). "In ovarian cancer cells, the downregulation of Bax and upregulation of Bcl-2 are associated with cisplatin resistance." (PMID 37742026, 2023). "The inhibitor of BCL-2/BCL-XL induces mitophagy that causes resistance to cisplatin in ovarian cancer cells." (PMID 36289190, 2022). "B7-H3 expression activates the PI3K/AKT signaling pathway and up-regulates Bcl-2 in protein levels, thereby causing chemoresistance in ovarian cancer." (PMID 35684481, 2022). "We therefore decided to test the effects of dinaciclib on the expression of some of these genes and found a significant reduction in BCL-2, expression of which has been linked to platinum resistance in resistant ovarian cancer models." (PMID 36505806, 2022). "Thence, PRSS1 overexpression caused the decrease in Bax/Bcl-2 ratio, which halted the apoptosis of ovarian cancer cells." (PMID 33585454, 2020). "Bcl-2 as well as Svv have been shown to be overexpressed in ovarian carcinomas and are associated with chemo-resistance and a worse prognosis." (PMID 32727400, 2020). "An imbalance of Bcl-XL/Bcl-2 to Bax expression can lead to suppressed apoptosis, and overexpression has been associated with chemoresistance in ovarian cancer." (PMID 33182737, 2020). "Immunohistochemical analysis revealed that Bcl-2 expression is detected mainly in EpCAM-positive cancer cells, confirming their association with Bcl-2 expression in ovarian cancer." (PMID 28574829, 2017). "In fact, decreased or phosphorylated Bcl-2 is implicated in the resistance of human ovarian cancer cells to tubulin polymerizing agents, such as paclitaxel." (PMID 27924151, 2016). "The initial split was rs11152377 of BCL-2, the most significant SNP out of those evaluated for ovarian cancer risk." (PMID 27462919, 2016). "In this study, we found the SNP that most significantly associated with ovarian cancer risk is rs11152377 located in the BCL-2 gene." (PMID 27462919, 2016). "SNP rs11152377 in BCL-2 gene showed the most significant effect on ovarian cancer risk with a recessive model." (PMID 27462919, 2016). "Consistent with the main effect derived from the logistic regression analysis, the rs11152377 located in the BCL-2 gene was at the initial split, thereby suggesting that this variant functions as the primary determinant of ovarian cancer risk." (PMID 27462919, 2016). "BCL2 is an important anti-apoptotic oncoprotein, known to promote chemotherapy resistance in ovarian cancer cells and to be associated with patient outcomes." (PMID 26717985, 2016). "In ovarian cancer cells, we showed that knockdown of BCL2 causes apoptosis and enhanced chemosensitivity, while overexpression of BCL2 partially rescues the effects of LARP1 depletion." (PMID 26717985, 2016). "Numerous studies suggesting an association of bcl-2 with the course of ovarian cancer were presented." (PMID 25018782, 2014). "Bcl-2 expression was found to be associated with the resistance of ovarian carcinoma to chemotherapy drugs." (PMID 23843871, 2013).
ovarian carcinoma (continued). "This study investigated the impact of siRNA-mediated MEG3 silencing in the context of dendrosomal nanocurcumin (DNC) and Oxaliplatin (OXA) treatments on ovarian cancer cell lines, focusing on the expression of genes associated with apoptosis and metastasis, including Bcl-2, BAX, MMP-2, and MMP-9." (PMID 41480643, 2026). "Activation of procaspases 3 and 9, downregulation of Bcl-2 protein, and upregulation of Bax (Bcl-2-associated X protein) protein also arresting the cell cycle at the G0/G1 phase in the ovarian cancer cell line were the identified mechanisms for a new coumarin compound, pulchrin A." (PMID 39364049, 2024). "Increased BCL2 protein expression in ovarian cancer tissues was also associated with tumor stage." (PMID 38003498, 2023). "Mechanistically, DSF treatment significantly reduced the expression of the anti-apoptosis marker B-cell lymphoma/leukemia-2 (Bcl-2) and increase the expression of the apoptotic molecules Bcl2 associated X (Bax) and cleaved caspase-3 to promote human epithelial ovarian cancer cell apoptosis." (PMID 37305383, 2023). "Based on the results obtained for the BCL2 polymorphism (rs2279115), it can be concluded that patients with the CC genotype and the C allele (48.98% vs. 39.50%, p = 0.039) show an increased risk of ovarian cancer." (PMID 38003498, 2023). "Based on the results obtained for the BCL2 polymorphism (rs2279115), it can be concluded that the patients with the CC genotype and the C allele (48.98% vs. 39.50%, p = 0.039) showed an increased risk of ovarian cancer." (PMID 38003498, 2023). "However, the results of various studies indicate an ambiguous level of BCL2 expression associated with ovarian cancer, which is a more complex molecular aspect in the pathogenesis of this cancer." (PMID 38003498, 2023). "High expression of RBP LARP1 co-associates with BCL2 and BIK in BCL2 messenger ribonucleoprotein (mRNP) complexes in epithelial ovarian cancer and stabilizes BCL2 while destabilizing BIK, which promotes ovarian cancer cell survival and leads to adverse prognosis." (PMID 33643390, 2021). "To examine this possibility, we collected lymphocytes from the peripheral blood of 12 ovarian cancer patients (seven samples with the reference sequence and five samples with the heterozygous 21 T > C variant), extracted RNA and quantified BCL2 mRNA levels, and compared them to actin using qRT-PCR." (PMID 31044156, 2019). "Previous studies have shown that Bcl-2 and Bcl-xL proteins appear to be involved in chemoresistance in ovarian carcinoma, and that reduced Bax expression is associated with cisplatin resistance in ovarian carcinoma cell systems." (PMID 22590594, 2012). "Studies on ovarian carcinoma cell lines have revealed an association between high BCL-2 levels and resistance to cisplatin, however, contradictory results have been published, too; BAX expression either enhanced or did not influence ovarian carcinoma cell lines sensitivity to cisplatin." (PMID 12644821, 2003). "The association of bcl-2 expression with better outcome has been reported in lung, breast, colon and ovarian carcinomas." (PMID 12454767, 2002).
ovarian carcinoma (continued). "Moreover, we found that deletion of EGFL6 could decrease the expression of Bcl-2 and increase the expression of Bax and Caspase-8, which could activate the Caspase-3 signal pathway and cause apoptosis of ovarian cancer cells." (PMID 32983976, 2020). "In addition, tumour xenografts derived from Oct4A knockdown cells displayed relatively lower abundance of markers associated with ovarian cancer including oncogenic markers Lin28 and Sox2, along with proliferation maker Ki67 and anti-apoptotic Bcl-2 expression." (PMID 26260289, 2015). "Earlier studies in our research group found the anticancer properties of DNC are mediated by regulating the expression of lncRNA MEG3 and apoptotic-associated markers of Bcl-2 and BAX in ovarian cancer." (PMID 41480643, 2026). "In PMOD-Chr, A2780 and OVCAR3 ovarian cancer cells, proapoptotic or apoptotic Bax, caspase 3 and 9 gene expressions significantly increased and anti-apoptotic Bcl2 decreased." (PMID 40938040, 2025). "The impact of BMX-001/PTX on BCL2 is noteworthy as this antiapoptotic protein (controlled by NF-кB pathway) is reportedly upregulated in ovarian cancer." (PMID 40900760, 2025). "Bioinformatics analysis demonstrated that EGCG affects NFκB1, Bcl-2, HIF-1α, MMP, etc., thereby reducing the risk of ovarian cancer." (PMID 41487287, 2025). "In summary, Our findings demonstrate that 6-gingerol induces ovarian cancer cell apoptosis through miR-506-mediated Gli3 suppression, providing an alternative to conventional Bax/Bcl-2-targeting approaches." (PMID 41018112, 2025). "The PPAA copolymers, especially those with lower HLB values, led to up to a 60% reduction in Bcl-2 gene expression in A2780 ovarian cancer cells." (PMID 40166479, 2025). "Quercetin has induced autophagy and apoptosis through ER (endoplasmic reticulum) stress via the p‐STAT3/Bcl‐2 axis in ovarian cancer SKOV‐3 cells." (PMID 40634118, 2025). "Analysis of ONCOMINE dataset revealed that paclitaxel-resistant ovarian cancer patients showed significantly higher expression of anti-apoptotic genes (Mcl-1, Bcl-2, Bcl-xL, and PARP) compared to paclitaxel-sensitive patients (P < 0.01)." (PMID 40599869, 2025). "Bioinformatic analyses indicated that high Bcl-2 and Survivin expression correlated with poorer overall survival in ovarian cancer patients." (PMID 41463522, 2025). "On the other hand, PGPIPN, a hexapeptide derivate from bovine β-casein residues 63–68, inhibited the proliferation of human ovarian cancer cells as well as the primary tumor growth via downregulation of BCL-2 signaling." (PMID 38990440, 2024). "Consistently, they demonstrated that PGPIPIN also inhibits the primary tumor growth rate in xenograft ovarian cancer model mice in a dose-dependent manner by promoting cell apoptosis through inhibition of BCL2 pathway and caspase-3 activation." (PMID 38990440, 2024). "The downregulation of the PI3K/AKT signaling pathway and the decrease in Bcl-2/Bax levels also indicated VM’s apoptotic potency on ovarian cancer cells." (PMID 38372808, 2024). "Here, we show that ASA inhibits the binding of CryZ to the mRNAs of Bcl-2 and Bcl-xl, two important anti apoptotic genes and that it is able to revert the drug resistance in ovarian cancer cells." (PMID 39021835, 2024). "The prognostic information of our five hub genes were determined using the KM plotter (SCN2A, ELAVL2, BCL2, MAF, and ZNF532,) to confirm the association between patterns of expression and metastasis risk in ovarian cancer patients." (PMID 38654363, 2024). "These authors also found that upon KLF8 overexpression, ovarian cancer cells display increased BCL2 expression that promotes cell survival." (PMID 38256218, 2024). "In another study on human ovarian carcinoma cell lines (HO-8910), esculetin was observed to dose- and time-dependently increased the Bax/Bcl-2 ratio." (PMID 39364049, 2024).
ovarian carcinoma (continued). "Accumulating evidence has revealed that BER exerts potential pro-apoptotic effects by modulating BAX/BCL2 (pro-/anti-apoptotic) expression in multiple cancers, including breast, lung, liver, gastric, colorectal, pancreatic, and ovarian cancers." (PMID 39275269, 2024). "In this manner, the increase in Bax expression and reduction in Bcl-2 expression promotes mitochondrial depolarization, an indication of proapoptotic characteristic in ovarian cancer cells." (PMID 39364049, 2024). "Bcl-2 and Bcl-xl play major roles in the pathobiology and chemoresistance of ovarian cancer, and their inhibitions were useful for treatment." (PMID 39021835, 2024). "Elevated levels of the anti-apoptotic protein Bcl-2 were present in urine from patients with ovarian cancer, independently from tumor stage, grade, and size, and differentiated between healthy and ovarian cancer patients with an AUC of 0.9." (PMID 38275400, 2024). "Other studies demonstrated that high concentrations of QCT induced endoplasmic reticulum stress via the p‐STAT3/Bcl‐2 axis in ovarian cancer cells, inducing apoptosis." (PMID 39162596, 2024). "The previous study observed a downregulation of the genes SCN2A, ELAVL2, ZNF532, MAF and BCL2 which were identified in ovarian cancer." (PMID 38654363, 2024). "Previous studies indicated BCL2 to be related to paclitaxel resistance in ovarian cancer, and up-regulation of BCL2L1 has been implicated in platinum and PARP inhibitor resistance in ovarian cancer." (PMID 38316463, 2024). "XTP8 promotes ovarian cancer cell proliferation while inhibiting apoptosis through the BCL2/BAX pathway." (PMID 38717641, 2024). "Blocking the function of MAM-localized BCL2, which interacts with IP3R, via a BCL2 inhibitor disrupts Ca2+ translocation and leads to an increase in the cellular Ca2+ level in cisplatin-resistant ovarian cancer cells." (PMID 38172597, 2024). "We demonstrated that IL-6, MDR-1, and BCL2 increased expression in the ovarian cancer cells co-cultured with macrophages." (PMID 36757936, 2023). "Other researchers demonstrated human ovarian cancer cells treated with simvastatin had increased caspase-3/7 activity and decreased pro-survival Bcl-2 and survivin mRNA levels." (PMID 37986175, 2023). "AM gene silencing decreased the expression of both AM mRNA and protein, blocked cell proliferation, and increased the chemosensitivity of HO8910 ovarian cancer cells via downregulation of Bcl-2/p-ERK expressions." (PMID 36980580, 2023). "In contrast, a high expression of BCL2 was observed in sensitive ovarian cancer cell lines (41M and CH1)." (PMID 38003498, 2023). "In our study, we analyzed the polymorphisms and expressions of the BCL2, BAX and c-MYC genes in patients with ovarian cancer." (PMID 38003498, 2023). "Further research on urinary bcl-2 as a biomarker for ovarian cancer, either alone or in combination with other markers, is warranted." (PMID 38068422, 2023). "Adenosine induces cell cycle arrest and apoptosis in ovarian cancer cell lines by down-regulating BCL-2." (PMID 37193964, 2023). "Anti-AM treatment and Bcl-2/ERK inhibited expressions are promising strategies to treat ovarian cancer." (PMID 36980580, 2023). "In our study, BCL2 expression was lower in tumor tissue similarly to ovarian-cancer-resistant cell lines." (PMID 38003498, 2023). "The BCL2 protein expression was low in ovarian-cancer-resistant cell lines, such as SKOV-3, 59M and OVCAR-3." (PMID 38003498, 2023).
ovarian carcinoma (continued). "TTK, mTOR, p-mTOR, AKT, p-AKT, 4EBP1, p-4EBP1, Bcl-2 are highly expressed in ovarian cancer, Bax, Caspase3 are lowly expressed in ovarian cancer, and cell apoptosis is inhibited, leading to the deterioration of ovarian cancer." (PMID 36849137, 2023). "LKBH5 can also enhance the stability of BCL-2 mRNA through demethylation and promote the proliferation and invasion of ovarian cancer cells." (PMID 37805597, 2023). "The Bcl-2 family has been reported to play a crucial role in the chemoresistance of ovarian cancer, and the molecules target Bcl-2 have shown efficacy in overcoming the chemoresistance of ovarian cancer." (PMID 37259418, 2023). "The aim of this study is to analyze the polymorphisms and expressions of the BCL2, BAX and c-MYC genes in patients with ovarian cancer." (PMID 38003498, 2023). "The present study investigated relationships between contrast kinetics in pathological tumour vessels in CEUS during preoperative examination and postoperative expression levels of CD105, CD34, and bcl-2 in patients with ovarian cancer." (PMID 38068422, 2023). "Linc00312 overexpression increased the cisplatin sensitivity via regulation of the Bcl-2 and caspase-3 pathways in cisplatin-resistant ovarian cancer cells." (PMID 36105363, 2022). "DX in contrast is an anti-cancer drug that induces UPR/ER stress and apoptosis by intercalating into a number of key DNA and RNA polymerases and altering the Bcl-2/Bax central checkpoint apoptosis pathways which are prevalent in ovarian cancer cells." (PMID 34800147, 2022). "Lewis y inhibits apoptosis and CAM-DR by activating the FAK signaling pathway and upregulating Bcl-2/Bcl-XL expression in ovarian cancer cell lines." (PMID 36544104, 2022). "MALAT1 elevated the expression of IL-1β, p-P38, p-NF-κB, COX2 and PGE2 signaling, and reduced caspase-3 level and promoted Bcl-2 expression in ovarian cancer cells." (PMID 36105363, 2022). "ALKBH5 suppressed autophagy and enhanced proliferation and invasion via BCL-2 and miR-7 in epithelial ovarian cancer." (PMID 36545327, 2022). "In epithelial ovarian cancer cells, overexpressed ALKBH5 in human ovarian cancer (SKOV3) cells enhanced the stability of BCL-2 mRNA and inhibited tumor cell growth and metastasis." (PMID 35707365, 2022). "ALKBH5 inhibits autophagy and promotes malignancy in ovarian cancer cells by stabilizing BCL2 mRNA and promoting BCL2 binding to BECN1." (PMID 35063010, 2022). "In ovarian cancer, the anti-apoptotic proteins Bcl-2 and Bcl-2-related gene long isoform (Bcl-xL) are often upregulated and correlated with poor prognosis of the disease." (PMID 36551731, 2022). "Knockdown of MALAT1 upregulated Bax protein and downregulated Bcl-2 protein in ovarian cancer cells." (PMID 36105363, 2022). "The spheroids exhibited increased expression of Bcl-2 compared to ovarian cancer cells cultured in monolayers." (PMID 36551731, 2022). "Previous study has shown that ALKBH5 promoted the expression of Bcl2 through regulating miR-7 in ovarian cancer." (PMID 35799597, 2022). "Conversely, Bcl-2, an anti-apoptotic protein, was significantly increased in ovarian cancer cells when ZNF252P-AS1 was down-regulated." (PMID 34980214, 2022). "It has been reported that the overexpression of BCL-2 antiapoptotic proteins increases resistance in ovarian cancer cells to cisplatin, paclitaxel, and other chemotherapeutic agents, both in vitro and in vivo." (PMID 36296636, 2022). "Several studies have shown that ALKBH5 inhibits Bcl2 degradation by reducing m6A modification, thereby regulating cell apoptosis in ovarian cancer, hepatocellular carcinoma and cerebral ischemia-reperfusion injury." (PMID 35799597, 2022). "Consistent with previous studies, BCL2 is upregulated in breast, prostate, colorectal, lung, stomach, ovarian cancer, and other solid tumors." (PMID 36445321, 2022).